RNU6-227P (RNA, U6 small nuclear 227, pseudogene)
Gene: Small nuclear RNA gene on chromosome 17 (76,656,320 to 76,656,422, forward strand). Ensembl gene ENSG00000199735.
Homologues: Orthologues: chimpanzee U6 (97% identical), macaque U6 (89% identical), guinea pig U6 (87% identical), mouse Gm22675 (73% identical). Paralogues in human: RNU6-1251P (90% identical), RNU6-11P (89% identical), RNU6-222P (89% identical), RNU6-379P (89% identical), RNU6-37P (89% identical), RNU6-43P (89% identical), RNU6-12P (88% identical), RNU6-13P (88% identical), RNU6-16P (88% identical), RNU6-24P (88% identical), RNU6-28P (88% identical), RNU6-32P (88% identical), and 1285 more.